COL14A1 (collagen type XIV alpha 1 chain)
Description:
Plays an adhesive role by integrating collagen bundles. It is probably associated with the surface of interstitial collagen fibrils via COL1. The COL2 domain may then serve as a rigid arm which sticks out from the fibril and protrudes the large N-terminal globular domain into the extracellular space, where it might interact with other matrix molecules or cell surface receptors (By similarity).
Synonyms: UND
Tractability: Antibody: its Gene Ontology location is reachable by antibodies, with high confidence; UniProt places it where antibodies can reach, with medium confidence; UniProt predicts a signal peptide or a membrane-spanning region.
Target class: Structural protein
Gene: Protein-coding gene on chromosome 8 (120,059,780 to 120,373,573, forward strand). Ensembl gene ENSG00000187955.
Subcellular location: Secreted, extracellular space, extracellular matrix
Subcellular location (Human Protein Atlas): Vesicles; Predicted to be secreted
Pathways (Reactome):
Extracellular matrix organization: Assembly of collagen fibrils and other multimeric structures; Collagen biosynthesis and modifying enzymes; Collagen chain trimerization; Collagen degradation
Gene Ontology:
Molecular function: RNA binding; collagen binding; extracellular matrix structural constituent; extracellular matrix structural constituent conferring tensile strength; protein-macromolecule adaptor activity
Biological process: cell-cell adhesion; collagen fibril organization; extracellular matrix organization
Cellular component: extracellular matrix; extracellular region; collagen trimer; collagen type XIV trimer; endoplasmic reticulum lumen; interstitial matrix
Genetic constraint (gnomAD): Loss-of-function variants: 111 observed, 193.09 expected, observed/expected ratio (o/e) 0.57, 90% interval 0.49 to 0.67. The upper end of that interval is the gene's LOEUF score, 0.67, which puts it in group 2 of 6, group 1 being the genes least tolerant of losing a copy. Missense variants: 1,747 observed, 2,046.7 expected, observed/expected ratio (o/e) 0.85, 90% interval 0.82 to 0.89. Synonymous variants: 694 observed, 733.35 expected, observed/expected ratio (o/e) 0.95, 90% interval 0.89 to 1.01.
Homologues: Orthologues: chimpanzee COL14A1 (99% identical), macaque COL14A1 (98% identical), rabbit COL14A1 (94% identical), pig COL14A1 (92% identical), dog COL14A1 (92% identical), mouse Col14a1 (90% identical), rat Col14a1 (88% identical), guinea pig COL14A1 (87% identical), tropical clawed frog col14a1 (68% identical), zebrafish col14a1a (62% identical), zebrafish col14a1b (24% identical). Paralogues in human: COL12A1 (47% identical), COL6A3 (20% identical), COL6A6 (19% identical), COL6A5 (18% identical), MATN2 (10% identical), VWA2 (9% identical), MATN4 (9% identical), MATN1 (8% identical), COCH (7% identical), VWA1 (6% identical), MATN3 (5% identical), VIT (5% identical).
Diseases named in the same sentence as COL14A1 in open-access papers:
COL14A1 is named in the same sentence as 63 diseases in open-access papers, as found by Europe PMC text mining. Sharing a sentence is not in itself a finding about the gene and the disease. The quoted sentences say what the papers report.
breast carcinoma (8 papers, 2011 to 2023). "Moreover, collagen binding results showed that high expression of COL14A1 is associated with poor overall survival rates for breast cancer patients." (PMID 38004422, 2023). "Expression levels of the ECM structural proteins Col5A1 and Col15A1 significantly decreased while Col14A1 significantly increased in lung fibroblasts exposed to factors from metastatic breast cancer cells as compared to controls." (PMID 37903851, 2023). "Recent reports suggest that ADAMTS2 is overexpressed by gastric cancer cells, COL14A1 is downregulated in breast cancer cells, and ADAMTS15 functions as a tumor suppressor role in prostate cancer." (PMID 37552338, 2023). "Also of note was the significant decrease in VCAM1 (2.6-fold), TBS2 (5.2-fold), MMP1 (7.7-fold), COL14A1 (2-fold), and MMP13 (3.3-fold), all of which have been associated with breast cancer cell invasion and metastasis to bone, lung, and/or the lymphatics." (PMID 29735912, 2018). "Several of the fused genes are also recurrently broken in a substantial proportion of breast cancers, as judged by copy number steps in array-CGH of 1000 breast tumours: around 10% have breaks in ERBB2, BCAS3 and SKAP1, while COL14A1, TIAM1, USP32, TAOK1 are broken in around 4%." (PMID 23260012, 2012). "In these terms, aside from the genes COL4A6, COL6A2 and COL14A1 belonging to the collagen family, Tenascin-X (TNXB), which was described as a metastasis signature in breast cancer, was also up-regulated in our experiment but has not previously been reported for gastric cancer." (PMID 21435268, 2011).
gastric cancer (6 papers, 2011 to 2023). A primary or metastatic malignant neoplasm involving the stomach. "COL14A1 is a significant mutant gene associated with the prognosis of gastric cancer, and can predict the survival of patients with newly classified subtypes of gastric cancer." (PMID 36869083, 2023). "Tumors with COL14A1 mutations for example had higher levels of macrophages, neutrophils and mast cells Mast cells have been associated with shorter OS in stomach cancer." (PMID 35120467, 2022). "To discover the function of COL14A1 and TNS1 in gastric cancer cells directly, we performed siRNA knockdown in human AGS cell line with two different siRNA sequences." (PMID 35515139, 2022).
renal cell carcinoma (5 papers, 2013 to 2023). "COL14A1 methylation is an unfavorable prognostic factor for renal cell carcinoma, and low COL14A1 expression seems to promote tumorigenesis of renal cell carcinoma." (PMID 36936416, 2023). "In renal cell carcinoma (RCC), which arises from epithelial cells, frequent hypermethylation of COL14A1 has been observed which resulted in transcriptional silencing; knockdown of COL14A1 increased the growth rate of RCC cell lines." (PMID 34095157, 2021). "COL14A1 aberrant methylation has been reported in ESCC, as well as in renal cell carcinoma, sarcomas, and endometrial carcinoma, whereas hypomethylation has been shown in coronary artery disease." (PMID 33292587, 2020).
cardiac hypertrophy (3 papers, 2018 to 2024). "Given the specific expression pattern of COL14A1 in endothelial cells uncovered by sc-RNA analysis, we speculate that the close association of COL14A1-activated endothelial cells and dysfunction in collagen constituents contributes to myocardial hypertrophy of HF progression." (PMID 38397416, 2024). "In animal studies, the lack of collagen type XIV alpha 1 chain (COL14A1) promotes pressure overload, resulting in myocardial hypertrophy, a critical step in the progression of HF45." (PMID 34593936, 2021).
Hepatic fibrosis (3 papers, 2009 to 2017). The presence of excessive fibrous connective tissue in the liver. "This may be a marker of some underlying pathology as Col14a1 has been associated with the rearrangement of connective tissue occurring in hepatic fibrosis." (PMID 19787071, 2009). "It is of note that Rbp1 expression changes have also been associated with hepatic fibrosis and thus the gene may be involved in the regulation of Col14a1." (PMID 19787071, 2009).
lung fibrosis (3 papers, 2021 to 2022). "A study on fibroblast heterogeneity even revealed that expression of COL14A1 marks a specific matrix-producing fibroblast subtype which increases in cell number in murine lung fibrosis." (PMID 34095157, 2021).
breast tumors (2 papers, 2012 to 2023). "We observed premetastatic lung increases in Col14A1, which encodes a subunit of collagen-1423, and which was consistent in premetastatic lungs of mice growing primary breast tumors, as well as lung fibroblasts exposed to metastatic cancer-conditioned media." (PMID 37903851, 2023).
keloid (2 papers, 2008 to 2022). An irregularly shaped, elevated mark on the skin caused by deposits of excessive amounts of collagen during wound healing. "As a result, there were 25 known keloid-related genes reported among the analyzed genes, whereas two pairs of them (COL14A1 and TNC, COL1A2 and PEPD) were co-occurred in the literature that mentioned the curated keyword 'keloid' (data not shown)." (PMID 18620599, 2008).
liver cancer (2 papers, 2023 to 2024). An epithelial or non-epithelial malignant neoplasm that arises from the liver. "Also, it has been identified that COL14A1 has an important role in keeping the stem cell-like and self-renewal features of Liver cancer stem cells through the activation of ERK signaling." (PMID 36978083, 2023).
osteoarthritis (2 papers, 2013 to 2021). A noninflammatory degenerative joint disease occurring chiefly in older persons, characterized by degeneration of the articular cartilage, hypertrophy of bone at the margins and changes in the synovial membrane. "The results showed that Col14a1 was tendon-associated collagen and was associated with the development of osteoarthritis." (PMID 34737845, 2021). "Col14a1 was identified in a microarray analysis of human tissue; while Bgn was previously associated with chondrogenesis and extracellular matrix turnover in osteoarthritis." (PMID 23382930, 2013).
renal carcinoma (2 papers, 2013 to 2014). A carcinoma arising from the epithelium of the renal parenchyma or the renal pelvis. "Previous studies have shown that aberrant COL14A1 DNA methylation has been tested in renal cancer cell lines and primary renal cancers, and the methylation correlated with silencing or down-regulating of mRNA expression." (PMID 25050929, 2014). "Moreover, RNAi-induced reduced expression of COL14A1 resulted in the growth of renal cancer cells in vitro." (PMID 25050929, 2014).
sarcoma (2 papers, 2013 to 2020). A usually aggressive malignant neoplasm of the soft tissue or bone. "A member of the collagen family (COL14A1) was selected to distinguish between sarcoma cluster 1 (mainly DDLS samples) and sarcoma cluster 3 (mainly PLS samples)." (PMID 24345474, 2013).
asthma (1 paper, 2024). "Collectively, our findings demonstrated that interactions between macrophages (Int Macro and Alv Macro) and fibroblasts (Col14a1 + Fib, Col14a1 + Fib/Myofib) played a pivotal role in both airway inflammation and remodeling in asthma." (PMID 38317239, 2024).
cardiomyopathies (1 paper, 2024). "Furthermore, they compared the genes with consistent change across all three cardiomyopathies to the druggable genome, resulting in 39 druggable genes (10 up-regulated and 29 down-regulated) including CYD2J2, MYH6, COL14A1, and SPARCL1." (PMID 37421484, 2024).
chronic pancreatitis (1 paper, 2011). A chronic inflammatory process causing damage and fibrosis of the pancreatic parenchyma. "The IHC analysis of lumican, versican and Col14A1 confirmed their up-regulation in chronic pancreatitis and pancreatic adenocarcinoma, and provided additional insights on how they behave at cellular level in association with the diseases." (PMID 22132114, 2011). "Although Col14A1 is a secreted protein, surprisingly, there is no staining of this protein in the ECM of chronic pancreatitis and pancreatic adenocarcinoma." (PMID 22132114, 2011).
Cirrhosis (1 paper, 2015). A chronic disorder of the liver in which liver tissue becomes scarred and is partially replaced by regenerative nodules and fibrotic tissue resulting in loss of liver function. "Patients with cirrhosis showed increased expression in blood of eight genes coding for collagen synthesis COL4A6, COL5A1, COL11A2, COL12A1, COL27A1, COL28A1, COL23A1, COL14A1." (PMID 26317806, 2015).
colorectal cancer (1 paper, 2019). A primary or metastatic malignant neoplasm that affects the colon or rectum. "NCI-H716 colorectal cancer cell line was included as a control, harboring an amplified full length FGFR2 kinase, whose hyper-activation is due to gene amplification and not to the presence of a concomitant fusion at the FGFR2 C-terminal with COL14A1 gene, conserving an intact kinase sequence." (PMID 31014245, 2019).
dilated cardiomyopathy (1 paper, 2025). Cardiomyopathy which is characterized by dilation and contractile dysfunction of the left and right ventricles. "First, three Hub genes (MYH6, ASPN, and COL14A1) associated with dilated cardiomyopathy-related HF were identified using a large-scale training dataset." (PMID 41158506, 2025). "MYH6, ASPN, and COL14A1 may be potential biomarkers for HF in dilated cardiomyopathy." (PMID 41158506, 2025).
familial adult myoclonic epilepsy (1 paper, 2021). "We also found hypermethylation of collagen type XIV, alpha 1 (Col14a1), an ECM component that is highly expressed in the brain and has been linked to familial adult myoclonic epilepsy (FAME)." (PMID 34831225, 2021).
fibrosis (1 paper, 2020). the formation of excess fibrous connective tissue in an organ or tissue in a reparative or reactive process. "In contrast, gene expression profiles in Col14a1+ MANCs from bleomycin-instilled mice did not display a gene expression profile associated with the development or maintenance of fibrosis, and very few DEGs were found in comparison with lung fibroblasts from naive mice, as previously reported." (PMID 33290280, 2020).
ischemic cardiomyopathy (1 paper, 2025). Ischemic cardiomyopathy is a cardiomyopathy in which a weakness in the muscle of the heart due to inadequate oxygen delivery to the myocardium with coronary artery disease being the most common cause. "Portokallidou has identified COL14A1 as a key gene in both dilated and ischemic cardiomyopathy through transcriptomic and proteomic analyses." (PMID 41158506, 2025).
lung adenocarcinoma (1 paper, 2022). A carcinoma that arises from the lung and is characterized by the presence of malignant glandular epithelial cells. "However, ISG15, COL14A1 and HBG2 are mainly decreased in lung adenocarcinoma." (PMID 35354498, 2022).
macular edema (1 paper, 2023). "RPCs increased the expression of Col8a1, Col14a1, Col16a1 and Col18a1, among them, Col18a1 has been reported to be associated with macular edema, neovascularization, and retinal detachment in DR26." (PMID 37670124, 2023).
melanoma (1 paper, 2025). A malignant, usually aggressive tumor composed of atypical, neoplastic melanocytes. "Many of these downregulated proteomic cargoes in melanoma sEVs, including collagens (COL1A1, COL3A1, COL6A1–A3, and COL14A1), matrix-associated proteoglycans (DCN, LUM, FMOD, OGN, and PRELP), and structural regulators (TNXB and PCOLCE), are key components of ECM organization and tensile strength." (PMID 41271007, 2025).
meningioma (1 paper, 2022). A generally slow growing tumor attached to the dura mater. "We found that the expression of COL2A1, and COL9A3 were significantly upregulated in meningioma tissues, and the expression of COL14A1, COL4A3, and COL4A2 was significantly down-regulated." (PMID 36538194, 2022).
metastasis (1 paper, 2025). The spread or migration of cancer cells from one part of the body (where they first appeared) to another. "Using LASSO Logistics analysis, they identified four genes (COL14A1, TNS1, NUSAP1, YWHAE) linked to peritoneal metastasis (PM) occurrence, where high COL14A1/TNS1 expression increased PM risk." (PMID 40906372, 2025).
osteoporosis (1 paper, 2025). A condition of reduced bone mass, with decreased cortical thickness and a decrease in the number and size of the trabeculae of cancellous bone (but normal chemical composition), resulting in increased fracture incidence. "The consistent expression patterns of key genes such as Col14a1 and CD248 in TSPC‐0 and their alignment with the pseudotime trajectory underscore their potential roles in the pathophysiology of osteoporosis." (PMID 40536433, 2025). "The expression patterns of key genes such as Col14a1 aligned with the pseudotime trajectory of TSPC‐0 cells, suggesting their involvement in the pathological state of osteoporosis." (PMID 40536433, 2025).
ovarian carcinoma (1 paper, 2023). A malignant neoplasm originating from the surface ovarian epithelium. "Studies have confirmed that COL14A1 is associated with the progression and metastasis of breast cancer, but there are few reports on the occurrence and development of ovarian cancer." (PMID 37024829, 2023). "The expression of COL14A1 in advanced ovarian cancer patients is significantly higher than that in early and middle ovarian cancer patients, which significantly affects the prognosis of patients." (PMID 37024829, 2023). "Among them, the THBS2 and COL14A1 genes had the most significant effect on the overall survival of ovarian cancer patients." (PMID 37024829, 2023). "We verified the expression of CCDC170, THBS2 and COL14A1 in ovarian cancer cells by Western blotting (WB) and immunofluorescence assay (IF)." (PMID 37024829, 2023). "Similarly, although THBS2 and COL14A1 also showed differential expression in ovarian cancer cell lines and normal ovarian cells, the results were not as significant as those for CCDC170." (PMID 37024829, 2023). "This indicates that CCDC170, COL14A1 and THBS2 are expected to become targets for the diagnosis and treatment of ovarian cancer." (PMID 37024829, 2023). "In addition, the expression of COL14A1 and THBS2 was significantly increased in ovarian cancer cell lines compared to normal ovarian cells (P < 0.05, P < 0.01), but the differential expression in CCDC170 was the opposite." (PMID 37024829, 2023). "In addition, we also used TCGA data to detect the expression of COL14A1, THBS2 and CCDC170 genes in different stages of ovarian cancer patients." (PMID 37024829, 2023).
periodontal disease (1 paper, 2025). "Additionally, we found a 190 bp insertion in COL14A1 associated with periodontal disease (OR = 4.97; 95% CI: 2.27–10.88; p = 8.9 × 10−4)." (PMID 41256123, 2025).
squamous cell carcinoma (1 paper, 2020). A carcinoma arising from squamous epithelial cells. "Moreover, COL14A1 methylation (COL14A1me) and GPX3 methylation (GPX3me) levels discriminated adenocarcinomas and squamous cell carcinomas, respectively, from normal samples (p = 0.002 and p = 0.009, respectively)." (PMID 33292587, 2020).
stomach cancer (1 paper, 2022). "COL14A1 was reported to have a nonsynonymous mutation rate of 4.4% in Microsatellite Stable (MSS) gastric tumors." (PMID 35120467, 2022).